IL6 (interleukin 6)
Diseases named in the same sentence as IL6 in open-access papers (continued):
Sharing a sentence is not in itself a finding about the gene and the disease.
Hydrocephalus (15 papers, 2015 to 2025). Hydrocephalus is an active distension of the ventricular system of the brain resulting from inadequate passage of CSF from its point of production within the cerebral ventricles to its point of absorption into the systemic circulation. "Microglia activation has been associated with both vasospasm and hydrocephalus and is closely regulated by the IL-6 pathway and NLRP3 inflammasome." (PMID 36114540, 2022). "Inflammatory markers such as IL-6 and IL-1β are elevated during CNS inflammation and can activate the NF-κB pathway, which is currently the only demonstrated mechanism—besides malignancy—linked to choroidal CSF hypersecretion and hydrocephalus development." (PMID 40722587, 2025). "A systematic review discussed inflammatory markers’ changes in hydrocephalus and reported that IL-6, IL-1β, and LRG were most consistently elevated in CSF from iNPH patients, while other markers showed limited or no consistent changes." (PMID 40722587, 2025). "We observed that ICH patients with hydrocephalus had higher levels of IL-6, IL-8, IL-10, and TNF-α in their CSF compared to those without hydrocephalus." (PMID 38167007, 2024). "This inflammatory milieu generates free radicals and pro-inflammatory cytokines such as interleukin (IL)-6, IL-4, tumor necrosis factor-α (TNFα), and transforming growth factor-β1 (TGFβ1), which contribute to the development and progression of hydrocephalus." (PMID 37794877, 2023). "An interesting correlation has been postulated regarding IL-6 surge, vasospasm, and hydrocephalus requiring shunting." (PMID 36114540, 2022). "IL-6 blockade prevented the ventriculomegaly consistent with hydrocephalus when compared to SAH with mean difference 0.09 (q = 8.38, p < 0.05)." (PMID 36114540, 2022). "We identified six inflammatory markers, IL-6, IL-1β, LRG, IL-18, VEGF, and IFN- γ, which were associated with the most evidence of increased levels in CSF from patients with hydrocephalus compared to control subjects." (PMID 33613789, 2021). "Given the previously-reported relationship between IL-6 and white matter damage in neonatal children and the presence of white matter damage in internal hydrocephalus, we also investigated the relationship between IL-6 and the aquaporins." (PMID 27357498, 2016). "The concentrations of AQP4 and IL-6 were increased in the cerebrospinal fluid of dogs with hydrocephalus compared to controls." (PMID 27357498, 2016). "Moreover, higher IL6 expression and lower TNF expression were associated with preoperative hydrocephalus." (PMID 38965454, 2024). "Hemorrhagic brain injury in the setting of GMH induces a substantial increase in the production of pro-inflammatory cytokines (IL-1β and IL-6) within the brain, which may consequently progress to hydrocephalus." (PMID 35720361, 2022). "IL-6 may therefore potentially promote choroidal CSF hypersecretion and hydrocephalus development by activating the NF-κB pathway." (PMID 33613789, 2021). "Future investigations such as the addition of supplemental MMP-9 and/or IL-10, or the addition of pharmaceuticals counteracting IL-6 and IL-8, could help in understanding if the severity of hydrocephalus can be reversed, paused or mitigated." (PMID 33514409, 2021). "Internal hydrocephalus is primarily a white matter disease and IL-6 levels may be used as a surrogate marker for white matter injury." (PMID 27357498, 2016). "Therefore AQP4 and IL-6 in CSF can be indicators of ventriculomegaly, of cellular damage, and of improvement after the treatment of hydrocephalus." (PMID 27357498, 2016). "In a hydrocephalus mouse model, Nec‐1 and GSK872 reduce necrotic cell death, effectively inhibit the phosphorylation of RIP3 and MLKL, and reduce the levels of inflammatory factors such as IL‐1β, IL‐6 and TNF‐α in the cortex and hippocampus." (PMID 34374150, 2021).
Hydrocephalus (continued). "IL-6, IL-1β, LRG, IL-18, VEGF, and IFN-γ are elevated in CSF from patients with hydrocephalus and may be involved in promotion of hydrocephalus development and progression." (PMID 33613789, 2021). "Therefore, the interplay of IL-6, IL-8, IL-10, MMP-7 and MMP-9 is worth future investigations to improve our understanding of the molecular and cellular events driving hydrocephalus." (PMID 33514409, 2021). "Furthermore, we assessed several proinflammatory cytokines, such as IL‐1β, IL‐6 and TNF‐α, by Western blotting, and the results showed that the expression levels of IL‐1β, IL‐6 and TNF‐α in the cortex and hippocampus were increased in the hydrocephalus group compared with the sham group at 28 days." (PMID 34374150, 2021).
hyperhomocysteinemia (15 papers, 2008 to 2024). A serious metabolic condition caused by mutations in the MTHFR gene, medications, or nutritional deficiency. "We hypothesize that the high fat diet (HFD) causes dysbiosis, systemic inflammation, and hyperhomocysteinemia (HHcy) in susceptible individuals, which subsequently elevate inflammatory cytokines such as IL-1β, IL-6, IL-17, and tumor necrosis factor alpha (TNF-α)." (PMID 32973741, 2020). "A cytokine stimulated by contracting skeletal muscles during exercise, hyperhomocysteinemia, and involved in the control of cell proliferation and apoptosis is Interleukin 6 (IL-6)." (PMID 36742002, 2022). "The hyperhomocysteinemia not only induced the secretion of Il-1β, Il-6, RANTES by monocytes, but also promoted inflammation via the TNFα induction, and subsequent MEF2 and NF-κB transactivation." (PMID 34771080, 2021). "For the underlying mechanism of transition process, previous studies have revealed the roles of TGFβ, hypoxia, angiotension II, endothelin-1, IL-6, hyperhomocysteinemia (HHcy), cylindromatosis (CYLD), nicotinamide adenine dinucleotide phosphate (NADPH) oxidase 4 (Nox4), and Fizzl." (PMID 34901214, 2021). "Another possible mechanism is that dysregulation of the transsulfuration pathway results in GDM via inflammation, supported by findings in an animal study that excessive methionine intake could induce a high level of hyperhomocysteinemia and interleukin-6 (IL-6)." (PMID 37764871, 2023). "Moreover, hyperhomocysteinemia may promote inflammatory processes via oxidative stress, by increased levels of cell adhesion molecules, cytokines (interleukin 6 and tumor necrosis factor-α) and chemokines (high-sensitivity C-reactive protein), which may contribute to the biology of cancer." (PMID 25985325, 2015).
intestinal tumor (15 papers, 2017 to 2025). "Recently published studies suggested that, among cytokines involved in intestinal tumor genesis associated with inflammation, an important role belongs to IL-6." (PMID 30154846, 2018). "The results found that PZH not only inhibited the increase in the number and volume of intestinal tumors in CAC mice but also suppressed the secretion of pro-inflammatory cytokines IL-6, TNF-α, and IL-1β in mouse serum." (PMID 39020410, 2024). "We also detected by qPCR that the IL-6 mRNA levels was higher in the stripped intestinal tumor tissues of ApcMin/+mice than in the normal intestinal epithelium of WT mice." (PMID 34863141, 2021). "In summary, MLKL exhibits a suppressive effect in the progression of intestinal tumors by regulating the IL-6/JAK2/STAT3 axis." (PMID 33767595, 2021). "ELISA analysis further found higher levels of IL-6 protein in the Apcmin/+Mlkl-/- intestinal tumors." (PMID 33767595, 2021). "IL-6 mRNA levels in intestinal tumors were increased compared with those in normal intestinal epithelial tissue, which echoes the data of increased serum IL-6 in clinical cancer patients." (PMID 34863141, 2021). "We found higher levels of IL-6 in the Apcmin/+Mlkl-/- intestinal tumors than in those of the Apcmin/+ mice." (PMID 33767595, 2021). "To explore the cellular source of this increased IL-6, we separated laminar propria lymphocytes (LPLs) and intestinal epithelial cells (IECs) from the intestinal tumors of Apcmin/+Mlkl-/- and Apcmin/+ mice." (PMID 33767595, 2021). "IL-6 is induced during gut injury and is necessary for intestinal repair after wounding which might also give rise to intestinal tumor formation." (PMID 35514976, 2022). "Thus, our results reveal that RIPK3 is a tumor suppressor in spontaneous intestinal tumorigenesis, and implicate targeting the IL-6/STAT3 signaling axis as a potential therapeutic strategy for intestinal tumor patients with reduced RIPK3." (PMID 33996591, 2021). "Our results also highlight that interfering with IL-6/STAT3 axis could be a better therapeutic option for intestinal tumor patients with low MLKL expression." (PMID 33767595, 2021). "Next, we sought to explore whether the IL-6/STAT3 axis contributed to the increase in intestinal tumors in Apcmin/+Mlkl-/-mice." (PMID 33767595, 2021). "However, given that conventional IL11 signaling and IL6 trans‐signaling both facilitate the growth of intestinal tumors, our observations do not address the relative contribution by which the bazedoxifene effect is mediated through inhibition of each of these mechanisms." (PMID 30885958, 2019). "ADAM17 is required for EGFR-induced intestinal tumors, apparently by shedding EGFR ligands to activate EGFR-dependent interleukin (IL)-6 synthesis in colonic myloid cells, which via IL-6 trans-signaling induces epithelial tumor formation." (PMID 29936496, 2018).
overnutrition (15 papers, 2013 to 2025). An imbalanced nutritional status resulting from excessive intake of nutrients. "Inflammaging refers to low-grade pro-inflammatory state in which cytokines such as TNF-α and IL-6 increase during the aging process, while metaflammation refers to metabolic inflammation due to metabolic diseases caused by overnutrition." (PMID 32961822, 2020). "In addition, S. pneumoniae detection was associated with higher concentration in plasma IL-6 only in children with overnutrition." (PMID 35886632, 2022). "In the myocardium, early overnutrition was associated with a significant increase in the gene expression of the proinflammatory markers IL-1β (p < 0.05), IL-6 (p < 0.01), TNF- α (p < 0.05), and LO (p < 0.05), and the pro-oxidant enzymes NOX-1 (p < 0.05) and NOX-4 (p < 0.01)." (PMID 32093229, 2020). "Chronic inflammation, characterised by elevated levels of IL-6, and overnutrition, such as consuming a high-fat diet, can inhibit the transcription of IRS genes." (PMID 41002997, 2025). "Multivariate regression models showed that the presence and loads of S. pneumoniae and M. catarrhalis were associated with higher concentrations of IL-6 in plasma and TNF-α in mucosal samples in children with overnutrition." (PMID 35886632, 2022). "Specifically, detection and loads of M. catarrhalis were associated with higher concentrations of IL-6 in plasma and TNF-α in nasopharyngeal samples only in children with overnutrition." (PMID 35886632, 2022). "The addition of sucrose at weaning, subsequent to neonatal overnutrition, also increased serum IL-1β and IL-6 levels and hypothalamic IL-6 mRNA levels." (PMID 31765625, 2020). "Moreover, in a state of overnutrition, visceral adipose tissue, liver, and pancreatic islets also secrete different inflammatory factors like interleukin-1β (IL-1β), interleukin-6 (IL-6), CRP, and various chemokines." (PMID 34557550, 2021). "Conditions such as obesity and overnutrition can lead to the excessive secretion of pro-inflammatory factors, such as TNF-α and IL-6, from adipose tissue." (PMID 41002997, 2025). "Overnutrition increases the levels of inflammatory molecules, such as TNF, IL-6, CCL2 and CCL3, in adipocytes, which activate resident macrophages, leading to the recruitment of more immune cells." (PMID 35112705, 2022). "Studies have shown that overnutrition can induce the nuclear transcription factor NF-κB to promote the expression of a variety of immune-inflammatory factors, such as TNF-α and IL-6, and trigger the tissue to enter a state of high immune-inflammatory activation." (PMID 35399795, 2022). "Neonatal overnutrition in rats leads to increased IL-6 serum levels and protein amounts in the hypothalamus and cerebellum, without concomitant changes in IL-6 mRNA levels, suggesting an increased uptake of circulating IL-6." (PMID 34201844, 2021). "The intestinal proinflammatory cytokines IL-6 and TNF-α pathway may be a novel target for reversing offspring glucose abnormalities affected by in utero overnutrition." (PMID 33240638, 2020).
polyp (15 papers, 2011 to 2025). A usually exophytic mass attached to the underlying tissue by a broad base or a thin stalk. "Because elevated IL-6 has been characterized as a pro-inflammatory cytokine, we expected its concentrations to be associated with polyp number and type." (PMID 24465801, 2014). "In this study, aspirin suppressed the mRNA expression levels of IL-6 in the small intestinal polyp region in Min mice." (PMID 38072949, 2023). "ApcMin/+ WT mice with severe cachectic symptoms and intestinal polyp burdens had high expression levels of IL6 and overexpression of IL6, which induced skeletal muscle wasting and polyp formation." (PMID 31650683, 2020). "Previous studies indicated that elevated IL-6 protein was observed in polyp tissue compared to middle turbinate in the same patients with CRSwNP." (PMID 31249603, 2019). "In our in vitro model of eosinohil inflammation, MF showed an inhibitory effect on FBS-induced IL-6, IL-8, GM-CSF, and sICAM-1 secretion in both nasal mucosa and polyp epithelial cell cultures." (PMID 21352574, 2011). "In the present study, we have shown that human nasal mucosa and polyp epithelial cells increased the release of IL-6, IL-8, GM-CSF, and sICAM-1 in response to FBS." (PMID 21352574, 2011). "A clear correlation between IL-6 concentration and the risk of polyp number or its type is not yet proven." (PMID 40149674, 2025). "Epithelial wound closure is significantly faster and CBF is significantly increased under IL-6 stimulation, which could induce an exaggerated epithelial response to external aggression and, in turn, promote polyp formation." (PMID 32209102, 2020). "Our hypothesis was that inflammatory cytokines in NPs, particularly IL-6, could be responsible for alteration of sinonasal epithelial cell functions (i.e. dysfunction of repair mechanisms and mucociliary clearance) thus creating favorable conditions for chronic inflammation and polyp growth." (PMID 32209102, 2020). "To assess the mechanisms underlying AHCC-mediated suppression of intestinal polyp formation, we evaluated the downstream targets of NRF2, such as MCP-1, and IL-6 mRNA expression in the non-polyp (mucosa) and polyp part of the intestine was investigated." (PMID 31777421, 2019). "IL6 and SPP1 transcripts were only detected in nine and eight cancer samples, respectively, and were nearly absent in polyp patients and controls, suggesting that transcript levels were generally lower and more cancer-specific, or that these RT-PCR assays were less efficient." (PMID 39523395, 2024).
rhabdomyolysis (15 papers, 2005 to 2025). Necrosis or disintegration of skeletal muscle often followed by myoglobinuria. "As revealed by several existing studies, the up-regulated levels of IL-6 will affect the ability of erythrocytes to carry oxygen, thus causing hypoxemia, or even rhabdomyolysis." (PMID 36814298, 2023). "The patients with septic shock exhibited significantly elevated IL-6 levels, while those with rhabdomyolysis demonstrated significantly elevated myoglobin levels." (PMID 41034327, 2025). "In LPS-induced rat models, procainamide treatment not only inhibits the overexpression of DNMT1 but also reduces the excessive production of IL-6 in rats with rhabdomyolysis, thereby improving renal function." (PMID 40766066, 2025). "TNFα, IL-1β and IL-6 levels were significantly increased in kidney tissue from CRAMP-/- mice subjected to the rhabdomyolysis model compared with the wild-type counterparts (p < 0.01, p = 0.02 and p = 0.03, respectively)." (PMID 33456345, 2021). "β-defensin 3, thus, together with NGAL, TNFα, IL-1β and IL-6 are the proinflammatory mediators directly responsible for the worst outcome of CRAMP-/- mice subjected to the rhabdomyolysis model." (PMID 33456345, 2021). "NLRP3 depletion decreased the mRNA expression of inflammatory cytokines, including TNF-α, IL-1β, and IL-6, induced by rhabdomyolysis." (PMID 33202867, 2020). "In our previous study, the antiarrhythmic drug procainamide inhibits the expression of DNA methyltransferase 1 (DNMT1) and diminishes IL-6 levels in rats with rhabdomyolysis." (PMID 27661616, 2016). "Overt DNA methylation and IL-6 production were significantly improved after treatment of LPS-induced rhabdomyolysis rats with DNMT1 inhibitor procainamide, indicating a crucial role of DNA methylation in the accumulation of pro-inflammatory cytokines." (PMID 26918767, 2016). "The rats in the LPS-induced rhabdomyolysis group exhibited obvious rises in the levels of plasma IL-6 at 6 h." (PMID 26918767, 2016). "The increases of lung DNMT1 expression and plasma IL-6 concentration were also observed in rhabdomyolysis animals induced by LPS." (PMID 26918767, 2016). "The levels of IL-6 increase exponentially with the intensity and duration of exercise; as does rhabdomyolysis and the consequent increase in serum CK levels correlated with IL-6 levels." (PMID 26237602, 2014). "On the day of the rhabdomyolysis onset, the patient had fever with increased IL-6, IL-10, and PCT." (PMID 35313994, 2022). "Our results provide in vivo evidence that LPS could induce DNMT1 overexpression and IL-6 overproduction resulting in clinical manifestations of rhabdomyolysis which can be improved with procainamide treatment." (PMID 26918767, 2016). "Effects of procainamide on plasma IL-6 levels in LPS-induced rhabdomyolysis rats." (PMID 26918767, 2016).
serous ovarian cancer (15 papers, 2012 to 2023). "A recent study reported higher plasma levels of interleukin 6 (IL6) in patients with high-grade serous ovarian cancer compared to benign tumours and healthy controls." (PMID 35406529, 2022). "Animal models for high-grade serous ovarian carcinoma have noted that knockout of IL-6 significantly reduces tumor growth, but when performed in combination with paclitaxel, there was accentuated cell kill." (PMID 32842701, 2020). "In most cases, patients with serous ovarian cancer had elevated values of Il-6." (PMID 37373969, 2023). "IL-6 alone may be a clinically reliable biomarker to distinguish between patients with advanced high-grade serous ovarian carcinoma and those with normal ovaries." (PMID 32042020, 2020). "Finally, we observed a significant decrease in TNF and IL6 production following CK2 inhibition with CX-4945 by ELISA in cell culture supernatant of primary cells derived from ascites of four high-grade serous ovarian cancer patients." (PMID 26871292, 2016). "The differential expression of CA125 between serous and non-serous ovarian cancer histotypes suggests that additional biomarkers such as CRP, SAA, IL6 and IL8 may complement the diagnostic efficacy of CA125, particularly for non-serous histotypes." (PMID 22410202, 2012). "Blocking the IL-6 feedback loop with tocilizumab or apigenin prevented PGCC formation, attenuated embryonic stemness and the CAF phenotype, and inhibited tumor growth in a patient-derived xenograft high-grade serous ovarian carcinoma model." (PMID 34588424, 2021).